STAT3 (signal transducer and activator of transcription 3)
Diseases named in the same sentence as STAT3 in open-access papers (continued):
Sharing a sentence is not in itself a finding about the gene and the disease.
infection (continued). "However, it remains to be seen if or how deletion of Stat3, Il15ra, or Il10r1 in these other populations might impact resistance to other infections or otherwise alter inflammatory and immune responses." (PMID 31552035, 2019). "However, infection with ACVR1 mutations and H3.1K27M did not significantly increase phosphorylated STAT3 Y705 expression compared to infection with ACVR1 mutations alone." (PMID 30833574, 2019). "The role of STAT3 during infection with M. tuberculosisin vivo is still unknown." (PMID 29338039, 2018). "However, the interaction between NF-κB and STAT3 and the relationships between ER stress and STAT3 undergoing CA16 infection in brain were largely unknown." (PMID 30186868, 2018). "The study sought to establish whether the infection of HGEC with live P. gingivalis would affect the mRNA expression of various genes potentially implicated in EGF signaling, mainly SOCS-3, IRF-1, EGF, EFGR, and STAT-3." (PMID 28748038, 2017). "STAT3 activation in response to incubation with IL-6 was also suppressed by T3 in macrophages, indicating that inhibition of IL-6 signalling by the thyroid hormones also occurs in these cells that have potent regulatory functions during infection and inflammation." (PMID 27484112, 2016). "The activation of STAT3 signaling in NI-BC thus suggests that cell to cell communication was initiated after M. tuberculosis uptake by macrophages and could be quantified as early as three hours post-infection." (PMID 27384401, 2016). "To address the potential contribution of STAT3 to infected B cell maturation, proliferation, and differentiation, we examined the entire B cell population in the spleens of mice at 16 dpi, representing an active phase of the host adaptive immune response, 16 days after intraperitoneal infection." (PMID 27486189, 2016). "Importantly, both viruses activate STAT3 almost immediately upon infection of primary cells." (PMID 27458446, 2016). "Notably, the number of IECs showing activation of Stat3 increased with progression of infection." (PMID 25799189, 2015). "Notably, interleukin-6 (IL-6) is a known inducer of STAT3 phosphorylation and has been implicated in maintaining B. abortus persistence in macrophages, but whether IL-6 intersects with other regulatory mechanisms of STAT3 during infection requires clarification." (PMID 41486271, 2026). "Collectively, these findings support a model in which E. chaffeensis exploits STAT3 via the TRP75 effector to activate an anti-apoptotic program and other cellular pathways that promote infection." (PMID 41115066, 2025). "The management of STAT3-HIES is primarily supportive and focuses on proactive infection prevention and control." (PMID 41458089, 2025). "Compared with Ad-GFP–infected cells, Ad-TET3 infection significantly enhanced TET3, STAT3, and H3K4me3 occupancy at the TGFB1 promoter." (PMID 40794443, 2025). "Both p-JAK1 and p-STAT3 were upregulated in CAR-TOAd−GFP and CAR-TTS−2021 cells, suggesting that the JAK-STAT pathway was activated in CAR-T cells following OAd infection." (PMID 40474210, 2025). "The number of activated T cells (subset 2) increased substantially after infection with upregulation of the IFNG, STAT3, STAT4, IL9, FOXP3, and TGFBR1, TGFBR2 genes." (PMID 40573402, 2025). "Given that E. chaffeensis is known to increase the expression of anti-apoptotic B-cell lymphoma 2 (BCL-2) family members and myeloid cell leukemia 1 (MCL-1) is a transcriptional target of STAT3, we investigated MCL-1 expression during infection." (PMID 41115066, 2025). "In RGNNV-infected fish cells, the subcellular distribution of phosphorylated STAT3 (Ec-STAT3) is altered, and the activity of the STAT3 promoter is significantly upregulated, indicating that STAT3 activation is involved in RGNNV infection." (PMID 41488475, 2025).
infection (continued). "Zhao’s research concluded that STAT3-mediated anti-apoptotic signaling protects against severe RSV infection in infants and mitigates both infection severity and inflammation in the lungs of affected children." (PMID 41020817, 2025). "Specifically, compared with infection at 18°C, GCRV infection at 28°C significantly induces IL-6 expression and STAT3 phosphorylation." (PMID 41488475, 2025). "To investigate the mechanism through which DCA promotes the infection of TGEV, we tested the effects of DCA on NF-κB and STAT3 phosphorylation." (PMID 38438836, 2024). "The study suggests that despite neutrophil dysfunction in STAT3 HIES, NANs have potential for directed delivery of cargo therapeutics to improve neutrophil infection clearance." (PMID 39134362, 2024). "In infection by Brucella abortus, the AK2/STAT3 pathway is important for the intracellular survival of the bacteria." (PMID 39255287, 2024). "In infection by other intracellular bacteria such as Brucella and Mycobacterium, the JAK2/STAT3 pathway is important for the intracellular growth and pathogenesis." (PMID 39255287, 2024). "To demonstrate the IAV-induced STAT3 nuclear translocation and the role of HDAC1 and HDAC2 in such translocation, we used an early infection timepoint, 6 h." (PMID 39861822, 2024). "Taken together, STAT3 activation in adult epithelial cells following RSV infection is required to prevent apoptosis and reduce severity of infection." (PMID 39484716, 2024). "Consistent with our results in the infection model, we found that the enhanced antitumor responses promoted by the heightened levels of LMO4 also depend on STAT3." (PMID 39117617, 2024). "Altogether, this suggests that different tegument proteins can modulate STAT3 and p38/MK2 activation negatively and positively, perhaps at different stages of infection." (PMID 37830871, 2023). "In addition, the STAT3 signaling pathway may play a detrimental role in the host defensive responses through the enhanced intracellular Mtb survival, blockade of apoptosis, and aggravation of inflammatory responses during infection and inflammation." (PMID 36882813, 2023). "It is known that STAT3 plays a vital role in the production and continuation of memory cell populations and that STAT4 is majorly involved at the site of infection and in stimulating tissue-resident memory responses." (PMID 36916966, 2023). "Patients with STAT3- HIES are prone to frequent pulmonary infection and other infection-related complications which lead to lung tissue destruction and significant mortality or morbidity; therefore, prompt diagnosis and prophylaxis initiation are critical." (PMID 37741967, 2023). "If this IL-24-mediated tissue injury response is analogous to pathogen infection where IFNs are upstream of STAT1/2, then IL-24 should be important for STAT3 activation in wounds." (PMID 37098344, 2023). "This study successfully established a mouse skin model of infection and found that POL can accelerate wound healing via STAT3 phosphorylated activation, which plays an important role in fungus-infected skin’s inflammatory response." (PMID 36364345, 2022). "To establish an in vitro infection protocol for B. taylorii, which enables the effector translocation via the VirB/VirD4 T4SS, we used the BepD-dependent STAT3 phosphorylation as sensitive readout." (PMID 35910598, 2022). "Treatment of the autoimmune and immune dysregulatory features of STAT3-GOF patients relies heavily on immunosuppression and is often challenging and fraught with complications including severe infections." (PMID 36843887, 2022). "The transcription levels of various signaling molecules, including IKKβ, p38, STAT1, STAT3, and STAT6, showed a sharp increase from day 6 after infection in HVEM−/− mice, compared with the rapid decrease at the same time in WT C57BL/6 mice." (PMID 35632787, 2022).
infection (continued). "The decreased phosphorylation of STAT3 and ERK was observed at 30 min post-infection with the treatment of the inhibitor AG1478 and gefitinib, but not at 10 min." (PMID 35847084, 2022). "The inhibited expression of P65, P38, and STAT3 adjusted by On-VIP was observed in vivo infection, similar to that in vitro infection." (PMID 36499231, 2022). "Mice were infected with T. cruzi and then treated daily from 70 to 91 days post infection (DPI) with TTI-101, a small molecule inhibitor of STAT3; benznidazole; a combination of benznidazole and TTI-101; or vehicle alone." (PMID 34504808, 2021). "In this study, we use an infection model to highlight that key signalling proteins like ERK, p38 MAPK and STAT3 are activated differently in senescent cells compared to their non-senescent counterparts." (PMID 34746026, 2021). "A recent report indicated that G-CSF is known to activate the phosphorylation of STAT3 via JAK2 and is involved in the maintenance of normal circulating granulocyte counts and in the neutrophilic response during infection." (PMID 34356683, 2021). "Given the critical role of STAT3 and MHV68 M2 in the regulation of B cell biology and differentiation, it is conceivable that the route of infection qualitatively alters the nature of the B cell differentiation induced and manipulated by MHV68 infection." (PMID 33824206, 2021). "Our previous results also indicated that STAT1 and STAT3 play critical roles in the regulation of UPEC invasion and infection in uroepithelial cells, especially those pretreated with glucose." (PMID 34946023, 2021). "This analysis revealed that STAT3 itself, and its targets such as CCNB1 and CCND1, were significantly downregulated in Hs 578T and MDA-MB-231 TNBC cells following shNONO infection." (PMID 32724453, 2020). "We detected phosphorylated p38 as early as 30 min post-infection, whereas phosphorylation of the canonical SOCS3-inducer STAT3 as well as STAT1 was observed only after 2 h." (PMID 33023610, 2020). "In spite of forming homodimers or heterodimers and translocating to the nucleus where they regulated the transcription of target genes, STAT3 and STAT1 played different even in part opposite roles in the process of pathogen infection." (PMID 32878239, 2020). "Infected mice with STAT3 knockout (KO) T cells produced less antibody and more Th1-like IFN-γ+IL-21−CXCR5lo effector and memory cells and were protected from re-infection." (PMID 32634740, 2020). "STAT3 TKO mice controlled a high-dose second challenge (1 × 107 iRBCs) completely, with infection becoming undetectable by day 3 post-reinfection (p.r.i)." (PMID 32634740, 2020). "The expression and activation of TFEB were enhanced early under the infection of S. aureus, which was followed by shrinkage to weaken lysosomal functions due to the delayed activation of ERK, mTOR, and STAT3." (PMID 33324360, 2020). "Infection by SARS-CoV-2 delivers into cells NSP1 and ORF6, which efficiently inhibit STAT1 function that in turn increases STAT3 activity." (PMID 33379366, 2020). "In normal hepatocytes, miR-122 strongly limits the phosphorylation of STAT3 by targeting three RTKs and other STAT3 activators, enabling a robust IFN response upon infection." (PMID 30735121, 2019). "TCID50 assay showed that after STAT3 knockdown, EV71 titer was reduced at various time points post infection." (PMID 31575039, 2019). "When we knocked down STAT3 with specific siRNAs, the restricted nuclear translocation of activated STAT1 was largely relieved post infection, leading to a recovered antiviral response by the downstream ISGs." (PMID 31575039, 2019). "The mRNA levels of NRF2 and STAT3 were found to be increased in a time-dependent manner in HCV-infected PHHs, whereas HNF4A mRNA levels were decreased over time post infection." (PMID 31547152, 2019).
infection (continued). "For example, the “calcium-induced T Lymphocyte Apoptosis,” “Aryl Hydrocarbon Receptor (AhR) Signaling,” “STAT3 Pathway,” and “PCK theta signaling in T lymphocytes” pathways were repressed to a greater extent during APEC O2-GFP infection." (PMID 31998322, 2019). "Consistent with an inverse relationship between IL-21 signaling and IFNα levels following infection with MRSA, IFNα levels were elevated in both serum and BAL fluid of the Stat3 mutant mice." (PMID 30969166, 2019). "On the other hand, M2 macrophage-related genes (PPARγ, TGF-β, STAT3, IL5 and STAT6) were significantly up regulated after 24 h of infection." (PMID 30918280, 2019). "The HDAC6 gene, involved in the HDAC6/STAT3/IL10 axis, was downregulated ~3-fold later on (24 hpi) during infection in JD(–) macrophages." (PMID 31969876, 2019). "Activation of STAT3 with cytokines such as CNTF or LIF decreases rod generation, and infection of ex vivo retinas with a dominant negative form of STAT3 prevents basal or CNTF-stimulated inhibition of photoreceptor development." (PMID 30364083, 2018). "Thereby infection stimulated activation would provoke a TLR-signaling primed positive feedback loop between the Notch cascade and STAT3 that sustains the activity of the key transcription factor." (PMID 30042932, 2018). "In conclusion, SAM protected brain cells from CA16 infection induced ER stress and inflammation through inhibiting PERK/STAT3/NF-κB signaling pathway." (PMID 30186868, 2018). "We also found that the activation of STAT3 and NF-κB by CA16 infection in PERK-siRNA transfected cells was significantly inhibited." (PMID 30186868, 2018). "Our data pointed toward that PERK /STAT3/NF-κB-dependent pathway driving inflammatory genes expression and cells injury in brain cells in response to CA16 infection." (PMID 30186868, 2018). "During infection, inflammation can induce hepcidin through the interleukin 6 (IL6)/ signal transducer and activator of transcription 3 (STAT3) pathway." (PMID 29324800, 2018). "Therefore, despite STAT3 expression in T cells is required for Th17 differentiation, STAT3 in APCs hampers secretion of Th17 promoting cytokines and the secretion of IL-17 by mycobacteria-specific T cells and reduces the resistance of mice to infection with M. tuberculosis." (PMID 29338039, 2018). "To gain insight into the mechanisms underlying the distinct transcriptional responses observed after infection with S. Typhimurium and S. Typhi, we examined the stimulation of MAPK, NF-κB, and STAT3 signaling pathways in cultured epithelial cells." (PMID 28742135, 2017). "Infection of BMDM and human macrophages with Mtb with esat-6 deletion induced diminished STAT3 activation and reduced IL-6 production compared to wild type and esat-6 complemented Mtb strains." (PMID 28106119, 2017). "Leptin signal sensitivity was significantly altered after leptin vectors infection as represented by the change of phosphorylation of JAK2 and STAT3." (PMID 29250056, 2017). "In mammals, IL-6 induction through STAT3 phosphorylation downregulates FOXP3 and blocks Treg cell differentiation while maintaining the Th17 response in order to continue dealing with the infection." (PMID 27069644, 2016). "Altogether, our results demonstrate that STAT3 is a dominant modulator of the immune response, controlling inflammation in M. tuberculosis-infected macrophages, which may be beneficial for the establishment of an intracellular niche for M. tuberculosis survival at the site of infection." (PMID 27384401, 2016). "ROS has been shown to activate STAT3 but much later after infection: 4 to 10 days after infection of primary B cells with EBV, ROS activated STAT3 while simultaneously inhibiting viral miRNAs that suppress LMP1 expression." (PMID 27458446, 2016). "The systems biology analysis identified multiple immune system and inflammation molecules (e.g., STAT3, STAT1, CEBPB, JUN, IGF1, SPP1, NFKB2, IL-1β, and CSF1) as master regulators that are activated upon infection." (PMID 26865111, 2016).
infection (continued). "Following infection of MRC-5 cells, an increase in nuclear localization of STAT3 compared to mock-infected cells was observed with the TBwt and TBrvIE1dl410-420 but not the TBIE1dl410-420 virus." (PMID 27387064, 2016). "Consistent with the role of STAT3 in IL-21-mediated IL-1β expression, Il1b mRNA was also lower in lungs from Stat3−/− than from WT mice after PVM infection." (PMID 26269257, 2015). "We evaluated the signaling pathways during the infection by measuring the expression of NF-κB (p65), TNF-α, IL-10 and STAT3 by Western blot analysis of hind paw supernatant of each group." (PMID 25973801, 2015). "For example STAT1 can be activated by type I interferon, STAT3 can be activated by growth factors (e.g. EGF, LIF) and NFκB can be activated by reactive oxygen species, infection and other inflammatory cytokines, including IL-1β." (PMID 26678048, 2015). "The expression of active phosphorylated (Y705) STAT3 (pSTAT3) was down-regulated by SINV at 24 h.p.i, suggesting a negative regulation of JAK/STAT pathway upon infection." (PMID 25343994, 2014). "Following 24 h of infection with H5N1-tyEng91 or H5N1-tyTR05 virus, members of JAK-STAT signalling pathway (JAK1, IFN-α receptor 1 [IFNAR1], STAT-3 and protein inhibitor of activated STAT 2 [PIAS2]) were down-regulated in chicken cells." (PMID 25431115, 2014). "STAT3, a bona fide TCPTP substrate, regulates the expression of genes involved in inflammatory reactions induced in response to tissue injury and infection." (PMID 24606867, 2014). "Using this approach, we found rapid necrosis of vaccinia-infected keratinocytes, and cytoplasmic accumulation of STAT3 and TAK1, within a few hours post-infection." (PMID 25419841, 2014). "In contrast to infection with live HCMV, decreased activation of STAT3 and JAK2 was observed in cells treated with UV-inactivated HCMV." (PMID 23555719, 2013). "During the third phase from day 5 until day 15 post-infection, transcriptional regulators STAT1 and STAT3 are highly expressed, together with IFNγ characteristic of CD4 T-lymphocyte activity." (PMID 23687968, 2013). "The most likely viral candidate to explain the STAT3 activation in our experimental model is IE1 protein, since it is highly expressed from day 1 to day 3 and then decreased at day 4 post-infection of HepG2 cells." (PMID 23555719, 2013). "Since STAT3 is a major controller of immune and inflammatory responses, we studied the role of SOCS3 in the control of infection with M. tuberculosis." (PMID 23853585, 2013). "In contrast, STAT3 phosphorylation was detected as early as 2 h post-infection in PHH and peaked again at day 3 post-infection." (PMID 23555719, 2013). "An example is ROP16 that manipulates the host cell transcription factors STAT3 and STAT6 in the early infection." (PMID 21592384, 2011). "We observed the mRNA level of EGFR to be up-regulated, and downstream signaling protein, such as STAT3, STAT1, AKT3 and MKK4 also showed up-regulation at 4 days post infection." (PMID 21172007, 2010). "Additionally, the virus appears to modulate transcription factors STAT3/STAT5, NELFE, ATF2, TAF7, and others, enhancing cellular response to infection." (PMID 40725231, 2025). "Concomitantly, genes involved in inflammatory and interferon-related responses, including IFN-γ, IL-12b, STAT1, STAT3, IL-6, TNF-α, CXCL9, CXCL10, and CXCL5, were significantly upregulated, indicating a strong pro-inflammatory environment during peak infection." (PMID 40630939, 2025). "Following infection, the EBOV VP24 protein antagonizes STAT3 to block IL-6-mediated signaling—consistent with IL-6 being one of the key cytokines that activate STAT3 during infections with various viruses (e.g., SARS-CoV-2, respiratory syncytial virus, and IAV)." (PMID 41488475, 2025). "Notably, 12 of these TFs exhibited distinct phosphorylation patterns upon infection, including MED14, SIN3A, BCL6, cJUN, NFATC1, STAT3, RUNX3, GTF2F1, MED1, JUNB, TLE3, and FOSL2." (PMID 40368139, 2025).